RHD (Rh blood group D antigen)
Description:
May be part of an oligomeric complex which is likely to have a transport or channel function in the erythrocyte membrane.
Synonyms: RhPII; CD240D; Rh30a; Rh4; RhPI; RhII; DIIIc; SLC42A5; HDFNRH; RH; RH30; RHCED; RHDVA(TT); RHDel; RHXIII; RhDCw; RhK562-II
Tractability: Antibody: a drug acting on it is in phase 2 or 3 trials; UniProt places it where antibodies can reach, with high confidence; its Gene Ontology location is reachable by antibodies, with high confidence; UniProt predicts a signal peptide or a membrane-spanning region. Other modalities: a drug acting on it is in phase 2 or 3 trials.
Gene: Protein-coding gene on chromosome 1 (25,272,393 to 25,330,445, forward strand). Ensembl gene ENSG00000187010.
Subcellular location: Cell membrane
Subcellular location (Human Protein Atlas): Nucleoplasm; Plasma membrane
Pathways (Reactome):
Metabolism: Rhesus blood group biosynthesis
Gene Ontology:
Molecular function: ammonium channel activity
Biological process: ammonium homeostasis; ammonium transmembrane transport
Cellular component: plasma membrane; membrane
Genetic constraint (gnomAD): Loss-of-function variants: 15 observed, 31.14 expected, observed/expected ratio (o/e) 0.48, 90% interval 0.32 to 0.74. The synonymous counts are far from expectation, so gnomAD's model fits this gene poorly and the ratio says little. Missense variants: 279 observed, 403.49 expected, observed/expected ratio (o/e) 0.69, 90% interval 0.63 to 0.76. Synonymous variants: 119 observed, 167.88 expected, observed/expected ratio (o/e) 0.71, 90% interval 0.61 to 0.82.
Homologues: Orthologues: macaque RHCE (77% identical), dog RHCE (61% identical), pig RHCE (61% identical), mouse Rhd (57% identical), rat Rhd (55% identical), tropical clawed frog rhd (36% identical), zebrafish rhd (35% identical), Drosophila melanogaster Rh50 (29% identical), Caenorhabditis elegans rhr-1 (28% identical), Caenorhabditis elegans rhr-2 (26% identical). Paralogues in human: RHCE (91% identical), RHAG (35% identical), RHCG (32% identical), RHBG (31% identical).
Diseases named in the same sentence as RHD in open-access papers:
RHD is named in the same sentence as 104 diseases in open-access papers, as found by Europe PMC text mining. Sharing a sentence is not in itself a finding about the gene and the disease. The quoted sentences say what the papers report.
anemia (13 papers, 2013 to 2025). A reduction in the number of red blood cells, the amount of hemoglobin, and/or the volume of packed red blood cells. "RhD alloimmunization can present as severe perinatal stress tCHI, anemia, and severe CHB, despite anti-D prophylaxis." (PMID 34838142, 2021). "Interestingly, two of the six modules (network modules 1 and 4) contained genes that code for proteins expressed in erythrocytes or other blood components (HBM, RHD, GYPA, GYPC, CA1), or have been implicated in blood-associated diseases like anemia (GYPA)." (PMID 32728112, 2020). "In the case of maternal RhD alloimmunization, the immune response against protein antigens of fetal RBCs may result in fetal anemia." (PMID 28717357, 2017). "We present a novel, pseudosyndromatic combination of severe tCHI, anemia, and severe CHB owing to RhD alloimmunization despite antenatal anti-D Ig prophylaxis." (PMID 34838142, 2021). "Antenatal problems identified were: 1) bacteriuria (43.2%); 2) maternal anemia (37%); 3) intestinal parasitic infections (59.2%); 4) sickle cell solubility test positive (13%); and 5) a RhD-negative phenotype (5.8%)." (PMID 36962895, 2022). "Chown was the first to demonstrate fetomaternal (macro) transfusion in an RhD-negative woman who had given birth to a baby with severe normoblastic anemia by detecting D-positive red blood cells in her circulation." (PMID 36431288, 2022). "The RhD alloimmunization HDN was not expected when the newborn presented with significant anemia, because of the antenatal prophylaxis, the negative antibody screens and the absence of recognized immunizing events." (PMID 34838142, 2021). "First, the IAT should be performed for all pregnant women, regardless of their RhD antigen status, since non-anti-D antibodies can also lead to fetal anemia." (PMID 31615430, 2019).
COVID-19 (9 papers, 2021 to 2025). A disease caused by infection with severe acute respiratory syndrome coronavirus 2. "(2022) conducted a study (n:180,564) that analyzed the correlation between the RhD antigen and COVID-19 risk." (PMID 38975325, 2024). "Despite the lack of statistical significance in the study’s outcomes, the potential association between blood types, the RhD antigen, and COVID-19 predisposition presented here should be further investigated." (PMID 38975325, 2024). "There are multiple associations between the different blood groups (ABO and RhD) and the incidence of oxidative stress-related diseases, such as certain carcinomas and COVID-19." (PMID 36984806, 2023). "It suggests that herd immunity may have been achieved in the last evaluated months, and highlights a potential link between the RhD antigen type and COVID-19 susceptibility." (PMID 38975325, 2024). "Likewise, the project shows the dynamics of seroprevalence over several periods and suggests a possible influence between blood types, the RhD antigen, and COVID-19 susceptibility." (PMID 38975325, 2024). "This study explores the role of genetic variations in blood group antigens, particularly ABO and RhD, in shaping mortality rates among critically ill COVID-19 patients in the southern region of Saudi Arabia." (PMID 38249239, 2023). "There are multiple associations between the different blood groups of the ABO and RhD system with the incidence of diseases, like certain carcinomas and COVID-19." (PMID 36984806, 2023). "Some studies have reported increased viral resistance in RhD-negative individuals, particularly against influenza A virus (potentially due to an amplified interferon-gamma signaling axis) and COVID-19." (PMID 41303137, 2025). "The distribution of COVID-19 patients on the ABO and RhD blood group demonstrated that blood group AB was more common in the COVID-19 group than the non-COVID-19 group." (PMID 35366803, 2022).
alloimmunization (8 papers, 2014 to 2025). An immune response to foreign (donor) antigens. "Despite the wide-spread use of anti-D immunoglobulins for the prevention of alloimmunization in our country, by far the most commonly implicated antigen in severe HDFN was RhD (12/16, 75.0 %)." (PMID 40491564, 2025). "This study sought to analyze the profile of fetuses, newborns and pregnant women with alloimmunization (anti-RhD) referred to and treated over the twenty years since the launch of the Rio de Janeiro State." (PMID 41341946, 2025). "RhD alloimmunization was reported in approximately up to 70% of severe HDFN cases, despite anti D HDFN being largely preventable." (PMID 39707247, 2024). "Since RhD alloimmunization is the most relevant, prevention methods are almostexclusively aimed at it." (PMID 38765509, 2024). "Routine care for the prevention of RhD alloimmunization in pregnancy and postpartum appears to be fairly consistent." (PMID 25491600, 2014). "Prevalence of RhD alloimmunization was higher in comparison to the literature." (PMID 40491564, 2025). "The rate of RhD alloimmunization is currently 0.3–0.6 % in developed countries." (PMID 40491564, 2025). "The rare possibility of HDN led to a delay in the diagnosis of RhD alloimmunization." (PMID 34838142, 2021). "The prophylaxis for the prevention of RhD alloimmunization was developed in the 1960s." (PMID 25491600, 2014). "For instance, before routine antenatal anti-D prophylaxis, this was the third most common alloantibody in pregnancies in Iceland (12.5% of detected alloantibodies) and the incidence of RhD alloimmunization was 6.1 per 1000 births of RhD negative women." (PMID 39707247, 2024).
toxoplasmosis (4 papers, 2009 to 2025). A parasitic disease contracted by the ingestion or fetal transmission of toxoplasma gondii. "The association between toxoplasmosis and the personality of RhD-negative and RhD-positive subjects was studied using Cattell's 16PF and Cloninger's TCI questionnaires." (PMID 23593448, 2013). "Here, we searched for differences in the toxoplasmosis-associated effects between RhD-positive and RhD-negative subjects by testing 502 soldiers with two personality tests and two intelligence tests." (PMID 23593448, 2013). "Subsequent studies suggested that the impact of RhD phenotype and genotype extends beyond toxoplasmosis, influencing various aspects of physical and mental health." (PMID 40722801, 2025). "The existence of a modifying effect of the RhD phenotype on the impact of toxoplasmosis on human performance was also confirmed by the results of a prospective case–control study conducted on a population of 3890 military drivers." (PMID 40722801, 2025). "Previous case-control study on a large sample of blood donors has shown that RhD-positive heterozygotes are resistant to pathological effects of toxoplasmosis while RhD-positive homozygotes are only temporarily resistant: their psychomotor performance decreases with length of infection." (PMID 19470165, 2009). "We suggest that RhD-negative drivers diagnosed with acute and subacute toxoplasmosis should be informed about the transiently increased risk of traffic accidents." (PMID 19470165, 2009). "One hundred and fifty-four (154, i.e. 31.4%) of 491 subjects with unambiguous results of the test for toxoplasmosis were Toxoplasma infected and 87 (17.3%) of 502 subjects were RhD negative." (PMID 23593448, 2013). "The fourth study has reported opposite relation of toxoplasmosis with Cattell's ego strength, praxernia, and ergic tension and Cloninger's cooperativeness in RhD-positive and RhD-negative blood donors." (PMID 23593448, 2013). "Results of a previous study suggested that in contrast to RhD-positive heterozygotes, the RhD-positive homozygotes were only transiently protected against some negative effects of toxoplasmosis (namely against prolongation of reaction times)." (PMID 23593448, 2013). "Another study examining the differences in the effects of toxoplasmosis between RhD-positive and RhD-negative individuals found that infected RhD-positive participants scored lower on intelligence measures than uninfected controls, whereas infected RhD-negative individuals showed higher scores." (PMID 40722801, 2025). "Many subjects were probably aware about their RhD phenotype; however, nobody was aware either about the hypothesis under study or about their toxoplasmosis status and therefore no systematic bias in the obtained data could be expected." (PMID 23593448, 2013).
hydrops fetalis (3 papers, 2022 to 2025). Hydrops fetalis is a severe and challenging fetal condition usually defined as the excessive accumulation of fetal fluid within the fetal extravascular compartments and body cavities that manifests as edema, pleural and pericardial effusion and ascites. "The disease is due to anti-RhD IgG antibodies crossing the placenta and destroying the RhD+ RBC in the reticuloendothelial system of the fetus and newborn, causing severe fetal anemia and hydrops fetalis in severe cases." (PMID 35844552, 2022).
parasitemia (3 papers, 2023 to 2024). "RhD- American Red Cross blood donors are more likely to have Bm infection and RhD- Bm-infected patients at Yale and Stony Brook Hospitals were found to have higher peak parasitemia percentages than those who were RhD+." (PMID 39330884, 2024). "Peak parasitemia was also significantly reduced among RhD+ individuals than RhD- individuals among babesiosis-hospitalized patients." (PMID 37375493, 2023). "Possible associations between RhD or ABO blood types and peak parasitemia, the length of hospital stay, and intensive care unit (ICU) admission were evaluated." (PMID 36696414, 2023). "Among hospitalized babesiosis patients from Connecticut, those with the RhD+ RBC antigen had lower peak parasitemia (p = 0.017), compared to those who were RhD-." (PMID 36696414, 2023). "Hospitalized RhD- babesiosis patients were more likely than RhD+ patients to have high peak parasitemia (p-value 0.017), which is a marker for disease severity." (PMID 36696414, 2023). "RhD+ patients were less likely (p-value 0.017) to have high parasitemia levels of >5%." (PMID 36696414, 2023).
thalassemia (3 papers, 2023 to 2025). An inherited blood disorder characterized by a decreased synthesis of one of the polypeptide chains that form hemoglobin. "Evidence summary and rationale: As with Recommendation 1 for SCD patients, no study from the updated review specifically compared limited matching (ABO and RhD) to the RhD, RhCcEe, and K‐matched approach for thalassaemia patients." (PMID 39535318, 2025). "Red blood cell (RBC) antigen matching beyond ABO and RhD is commonly recommended for patients with sickle cell disease (SCD) and thalassaemia." (PMID 39535318, 2025). "Previous evidence‐based guidelines have provided recommendations for prophylactic RBC matching beyond ABO and RhD in patients with SCD and thalassaemia aimed at reducing risks of alloimmunisation." (PMID 39535318, 2025). "Recommendation 4: Patients with thalassaemia who do not have any known alloantibody(ies) should be transfused with ABO, RhD, RhCcEe, and K‐matched RBCs to reduce the risk of alloimmunisation and delayed HTRs (low quality of evidence, weak recommendation)." (PMID 39535318, 2025). "Our current transfusion practice does not provide the Rh phenotype-matched blood to all patients but only for transfusion-dependent thalassemia and RhD negative, which can explain the Rh alloimmunization in most of our CLD patients." (PMID 36900030, 2023).
viral infection (3 papers, 2016 to 2025). "Several association studies have found a relationship between RhD negativity and enhanced resistance to viral infection." (PMID 35428875, 2022). "The Rhesus D antigen (RhD) has been associated with susceptibility to several viral infections." (PMID 35428875, 2022). "However, many RhD negative women carry a RhD negative fetus and, thus, receive anti-D unnecessarily, exposing them to the risks associated with administration of human blood products that have been associated with serious viral infections in the past." (PMID 27036548, 2016). "We were particularly interested to compare RhD-positive and -negative males and females, as sex is emerging as a key factor in determining outcomes to viral infection, especially SARS-CoV-2 and influenza." (PMID 35428875, 2022).
atherosclerosis (2 papers, 2024 to 2025). A disease characterized by the build-up of fatty material and calcium deposition in the arterial wall resulting in partial or complete occlusion of the arterial lumen. "Previous studies are scarce for the RhD blood group, but we recently showed that RhD − young individuals are associated with subclinical atherosclerosis." (PMID 39844181, 2025). "Studies assessing the roles of ABO and RhD in subclinical atherosclerosis as potential risk markers are sparse, and the studies available have primarily included individuals already considered high-risk." (PMID 38592146, 2024). "We aimed to determine whether the ABO and RhD blood groups are associated with subclinical atherosclerosis in a healthy population." (PMID 38592146, 2024). "In conclusion, we found the hereditary RhD factor to be associated with subclinical atherosclerosis, represented by an increased CIMT in younger RhD− individuals, indicative of the RhD blood group system as a mediator in atherosclerosis." (PMID 38592146, 2024). "Still, we think there is an indication that RhD has a role in the development of atherosclerosis in young individuals with a hereditary component." (PMID 38592146, 2024). "In this study, we found an association between the RhD blood group and subclinical atherosclerosis in 40-year-olds, represented by RhD negative individuals having an increased CIMT compared to RhD+ individuals." (PMID 38592146, 2024).
Babesia infection (2 papers, 2023). "However, this same study found RhD+ individuals to be less susceptible to Babesia infection than RhD- individuals." (PMID 37375493, 2023). "People expressing RhD antigen may have a decreased risk of B. microti infection and babesiosis severity." (PMID 36696414, 2023). "In this study, we sought to determine if RhD and ABO RBC antigens are associated with B. microti infection, as determined by B. microti 18S rRNA, or babesiosis disease severity." (PMID 36696414, 2023). "Thus, data from both our blood donor and hospitalized babesiosis patient populations suggest that the RhD antigen may play a role in inhibiting B. microti entrance and/or proliferation within RBCs." (PMID 36696414, 2023). "Future studies should quantify the impact of RhD, ABO, and other RBC antigens on Babesia infection, and the mechanisms by which they impact RBC invasion and babesiosis severity." (PMID 36696414, 2023).
coagulation disorders (2 papers, 2025). "Eligible patients were those at high risk for platelet transfusion, identified by risk prediction score or clinician judgment, excluding female patients aged 18 to 55 years who were rhesus D (RhD) negative or with unknown RhD status and patients with coagulopathy or prior thromboembolism." (PMID 41360729, 2025).
Hypertension (2 papers, 2021 to 2024). The presence of chronic increased pressure in the systemic arterial system. "RhD-negative patients had a lower age at diagnosis (p=0.035) with a mean age of 48 years compared with a mean age of 55.8 years in patients with positive RhD, and a lower rate of hypertension (6.7% in RhD-negative vs 35.2% in RhD-positive, p=0.035)." (PMID 39132152, 2024). "Regarding common comorbidities such as hypertension, we found that RhD-positive patients were associated with a higher risk of hypertension compared to RhD-negative patients." (PMID 39132152, 2024). "For the RhD positive as compared to RhD negative, only one disease category remained statistically significant after Bonferroni adjustment, namely pregnancy-induced hypertension (IRR 1.12; 95% CI, 1.09–1.16)." (PMID 33902814, 2021).
lung carcinoma (2 papers, 2016 to 2025). "Limitations of present study: Onset of disorders associated negatively with the frequency of RhD positive heterozygotes, e.g. liver and lung cancer, is rather high in modern human." (PMID 26811928, 2016). "Many (but not all) of the disorders observed to be affected by RhD phenotype, such as cardiovascular diseases, lung cancer, liver cancer, asthma, could be considered as “modern” diseases." (PMID 26811928, 2016).
malaria (2 papers, 2022). Malaria is a serious and sometimes fatal disease caused by a parasite that commonly infects a certain type of mosquito which feeds on humans. "Significant associations were observed between RhD +ve and RhD −ve among the malaria infected donors (A: χ2 = 26.618, p = 0.001; AB: χ2 = 23.540, p = 0.001; B: χ2 = 5.419, p = 0.020; O: χ2 = 68.701, p = 0.001)." (PMID 35888577, 2022).
Miscarriage (2 papers, 2017 to 2025). A pregnancy that ends at a stage in which the fetus is incapable of surviving on its own, defined as the spontaneous loss of a fetus before the 22th week of pregnancy. "Parity ranged from one to eight, and few women were multiparous or had previous miscarriage, except in the RhD−/IAT+ group, in which almost one-third of the women had had at least one miscarriage." (PMID 28717357, 2017).
pregnancy-induced hypertension (2 papers, 2021 to 2022). "Recently, another research group expanded previous knowledge on other associations such as pregnancy-induced hypertension RhD positive, as compared to negative." (PMID 35735664, 2022).